RN7SKP123 (RN7SK pseudogene 123)
Gene: Miscellaneous RNA gene on chromosome 1 (93,026,252 to 93,026,542, forward strand). Ensembl gene ENSG00000222664.
Homologues: Orthologues: chimpanzee 7SK (81% identical), guinea pig 7SK (49% identical), mouse Gm55664 (48% identical), mouse Gm54997 (47% identical), mouse Gm54777 (20% identical). Paralogues in human: RN7SKP124 (66% identical), RN7SKP217 (65% identical), RN7SKP30 (64% identical), RN7SKP47 (64% identical), RN7SKP90 (64% identical), RN7SKP208 (63% identical), 7SK (63% identical), RN7SKP133 (62% identical), RN7SKP225 (62% identical), RN7SKP250 (62% identical), RN7SKP294 (62% identical), RN7SKP1 (62% identical), and 284 more.